UTS2R (urotensin 2 receptor)
Description:
G protein-coupled receptor for the vasoactive neuropeptides urotensin-2 and urotensin-2B. Upon ligand binding, activates intracellular signaling cascades via G protein coupling, primarily through Gq/11, leading to phospholipase C activation, increased intracellular calcium, and activation of protein kinase C (PKC). Through coupling to G(i)/G(o) alpha subunits, stimulates MAPK/ERK pathways and thereby contributes to regulation of vascular tone, cardiac contractility, and cell proliferation. Ligand binding also triggers a marked reduction in the biogenesis of autophagosomes by inhibiting the recruitment of ATG16L1 to pre-autophagosomal endocytic vesicles.
Synonyms: UR-2-R; GPR14; UTR; UTR2
Tractability: Small molecule: a drug acting on it is in phase 2 or 3 trials; a high-quality ligand is known; it belongs to a druggable protein family. Antibody: its Gene Ontology location is reachable by antibodies, with high confidence; UniProt places it where antibodies can reach, with medium confidence; UniProt predicts a signal peptide or a membrane-spanning region. PROTAC: a small molecule that binds it is known.
Target class: Peptide receptor (family A GPCR); Family A G protein-coupled receptor; Short peptide receptor (family A GPCR); Membrane receptor; Neuropeptide receptor
Safety:
Unwanted effects reported when the protein is acted on. In parentheses: how it was acted on, where the effect was seen, and who reports it.
decreased blood glucose (inhibition, acute dosing; renal, cardiovascular; source: Lynch et al. (2017))
decreased blood pressure (inhibition, acute dosing and activation, acute dosing; renal, cardiovascular; source: Lynch et al. (2017))
decreased cardiac contractility (activation, acute dosing; renal, cardiovascular; source: Lynch et al. (2017))
decreased inflammation (inhibition, acute dosing; renal, cardiovascular; source: Lynch et al. (2017))
decreased urinary potassium excretion (activation, acute dosing; renal, cardiovascular; source: Lynch et al. (2017))
decreased urinary sodium excretion (activation, acute dosing; renal, cardiovascular; source: Lynch et al. (2017))
decreased urine excretion (activation, acute dosing; renal, cardiovascular; source: Lynch et al. (2017))
increased urinary sodium excretion (inhibition, acute dosing; renal, cardiovascular; source: Lynch et al. (2017))
increased urine excretion (inhibition, acute dosing; renal, cardiovascular; source: Lynch et al. (2017))
Gene: Protein-coding gene on chromosome 17 (82,368,266 to 82,377,709, forward strand). Ensembl gene ENSG00000181408.
Subcellular location: Cell membrane
Pathways (Reactome):
Signal Transduction: G alpha (q) signalling events; Peptide ligand-binding receptors
Gene Ontology:
Molecular function: protein binding; G protein-coupled receptor activity; urotensin II receptor activity
Biological process: blood circulation; neuropeptide signaling pathway; regulation of blood pressure; signal transduction; blood vessel diameter maintenance; G protein-coupled receptor signaling pathway
Cellular component: plasma membrane; membrane
Genetic constraint (gnomAD): Missense variants: 469 observed, 352.82 expected, observed/expected ratio (o/e) 1.33, 90% interval 1.23 to 1.43. Synonymous variants: 245 observed, 169.46 expected, observed/expected ratio (o/e) 1.45, 90% interval 1.3 to 1.61.
Homologues: Orthologues: chimpanzee UTS2R (99% identical), macaque UTS2R (95% identical), Drosophila melanogaster AstC-R1 (21% identical), Caenorhabditis elegans npr-32 (20% identical), Caenorhabditis elegans npr-16 (19% identical), Caenorhabditis elegans npr-24 (18% identical). Paralogues in human: SSTR4 (26% identical), OPRD1 (24% identical), OPRK1 (24% identical), OPRL1 (24% identical), SSTR3 (24% identical), OPRM1 (24% identical), SSTR5 (24% identical), SSTR1 (23% identical), SSTR2 (23% identical), LTB4R2 (22% identical), LTB4R (22% identical), NPBWR2 (22% identical), and 5 more.
Diseases named in the same sentence as UTS2R in open-access papers:
UTS2R is named in the same sentence as 30 diseases in open-access papers, as found by Europe PMC text mining. Sharing a sentence is not in itself a finding about the gene and the disease. The quoted sentences say what the papers report.
cardiac hypertrophy (2 papers, 2015 to 2020). "UTS2R has been shown to have a potential link to cardiac remodeling such as hypertrophy." (PMID 26070612, 2015).
anaplastic astrocytoma (1 paper, 2021). "QPCR analyses of mRNAs encoding UII, URP, and UT in the SW1088 (anaplastic astrocytoma) and in U87, U251, 8MG, and 42MG GBM cell lines here established that expression levels were non-homogeneous and higher for UTS2R in 8MG and 42MG, UTS2 in U87, and UTS2D in SW1088." (PMID 33937253, 2021).
glioma (1 paper, 2021). A benign or malignant brain and spinal cord tumor that arises from glial cells (astrocytes, oligodendrocytes, ependymal cells). "Within the four groups of GBM along with the Verhaak classification, UTS2R (UT) and UTS2D (URP) were expressed in all groups of GBM, but importantly, UTS2 (UII) exhibited a net higher expression in the mesenchymal subgroup, suggesting that UII may be associated with glioma prognosis." (PMID 33937253, 2021).
renal failure (1 paper, 2019). "It is worth noting that although protein expression for urotensin system components was high, particularly in the kidneys from the SNx‐L group that were killed immediately before renal failure, attempts to quantify Uts2, Uts2b and Uts2r (UT receptor) mRNA were unsuccessful." (PMID 30575177, 2019).
type II diabetes (1 paper, 2017). "Another unexpected recent finding is the location of UTS2R which is associated with development of type II diabetes and fat deposition." (PMID 28913347, 2017).
cancer (4 papers, 2009 to 2024). A tumor composed of atypical neoplastic, often pleomorphic cells that invade other tissues. "Cluster 2 contains instead receptor-ligand axes that are more frequently concordantly downregulated in cancer subtypes, although several of these might still be concordantly upregulated in specific subtypes (e.g., CXCR2, EDNRB, FFPR2, or LGR6, GALR2, and UTS2R)." (PMID 38723607, 2024).
UTS2R also shares sentences with these, for which no sentence is quoted: heart failure (3 papers); Hypertension (3); atherosclerosis (2); bladder cancer (2); prostate carcinoma (2); renal fibrosis (2); tumor (2); adrenocortical tumor (1); aortic valve stenosis (1); asthma (1); breast carcinoma (1); candidiasis (1); cardiovascular diseases (1); cervical cancer (1); Cirrhosis (1); disseminated candidiasis (1); fungal infection (1); glioblastoma (1); hypertrophy (1); infection (1); Infertility (1); neuroblastoma (1); pulmonary hypertension (1); renal cell carcinoma (1).